RN7SL184P (RNA, 7SL, cytoplasmic 184, pseudogene)
Gene: Miscellaneous RNA gene on chromosome 4 (113,419,840 to 113,420,136, forward strand). Ensembl gene ENSG00000239279.
Homologues: Orthologues: chimpanzee Metazoa_SRP (99% identical), macaque Metazoa_SRP (94% identical). Paralogues in human: RN7SL2 (83% identical), RN7SL1 (82% identical), RN7SL444P (81% identical), RN7SL3 (80% identical), RN7SL322P (80% identical), RN7SL45P (79% identical), RN7SL597P (79% identical), RN7SL44P (79% identical), RN7SL451P (79% identical), RN7SL709P (79% identical), RN7SL769P (78% identical), RN7SL147P (78% identical), and 705 more.